MAP7 (microtubule associated protein 7)
Description:
Microtubule-stabilizing protein that may play an important role during reorganization of microtubules during polarization and differentiation of epithelial cells. Associates with microtubules in a dynamic manner. May play a role in the formation of intercellular contacts. Colocalization with TRPV4 results in the redistribution of TRPV4 toward the membrane and may link cytoskeletal microfilaments.
Synonyms: E-MAP-115; EMAP115
Tractability: Small molecule: a structure with a bound ligand is known. Antibody: UniProt places it where antibodies can reach, with medium confidence; its Gene Ontology location is reachable by antibodies, with medium confidence. PROTAC: UniProt records ubiquitination sites on it; its protein half-life has been measured.
Target class: Structural protein
Gene: Protein-coding gene on chromosome 6 (136,342,281 to 136,550,819, reverse strand). Ensembl gene ENSG00000135525.
Subcellular location: Cytoplasm, perinuclear region; Basolateral cell membrane; Cytoplasm, cytoskeleton
Subcellular location (Human Protein Atlas): Cytosol; Microtubules
Gene Ontology:
Molecular function: protein binding; signaling receptor binding; structural molecule activity
Biological process: establishment or maintenance of cell polarity; microtubule cytoskeleton organization; protein localization to plasma membrane; response to osmotic stress
Cellular component: cytosol; microtubule cytoskeleton; axon; microtubule associated complex; basolateral plasma membrane; cytoskeleton; perinuclear region of cytoplasm
Genetic constraint (gnomAD): Loss-of-function variants: 46 observed, 78.57 expected, observed/expected ratio (o/e) 0.59, 90% interval 0.46 to 0.75. The upper end of that interval is the gene's LOEUF score, 0.75, which puts it in group 3 of 6, group 1 being the genes least tolerant of losing a copy. Missense variants: 882 observed, 887.2 expected, observed/expected ratio (o/e) 0.99, 90% interval 0.94 to 1.05. Synonymous variants: 326 observed, 326.35 expected, observed/expected ratio (o/e) 1, 90% interval 0.91 to 1.1.
Homologues: Orthologues: chimpanzee MAP7 (96% identical), macaque MAP7 (93% identical), pig MAP7 (84% identical), dog MAP7 (84% identical), rabbit MAP7 (82% identical), mouse Map7 (79% identical), rat Map7 (74% identical), guinea pig MAP7 (72% identical), tropical clawed frog map7 (47% identical), zebrafish map7b (44% identical), Drosophila melanogaster ens (25% identical), zebrafish map7a (25% identical). Paralogues in human: MAP7D1 (35% identical), MAP7D2 (29% identical), MAP7D3 (22% identical).
Diseases named in the same sentence as MAP7 in open-access papers:
MAP7 is named in the same sentence as 26 diseases in open-access papers, as found by Europe PMC text mining. Sharing a sentence is not in itself a finding about the gene and the disease. The quoted sentences say what the papers report.
cervical cancer (10 papers, 2020 to 2024). A primary or metastatic malignant neoplasm involving the cervix. "MAP7 has been shown to be highly in breast cancer and cervical cancer, where it enhances the invasion and migration of breast cancer and cervical cancer cells." (PMID 39980969, 2024). "MAP7 promotes cervical cancer cell line migration and invasion, and epithelial-mesenchymal transition (EMT), by regulating autophagy." (PMID 36968845, 2023). "At the same time, MAP7 has also been reported to promote the EMT process of human cervical cancer cells by regulating the autophagy pathway and accelerate the tumor progression of cervical cancer." (PMID 34660263, 2021). "We scanned the most authoritative database in cancer-TCGA database and identified MAP7 was upregulated in 306 Cervical cancer compared with normal tissue." (PMID 31956295, 2020). "Taken together, our research shows that MAP7 promotes migration and invasion and progression of human cervical cancer through modulating the autophagy pathway." (PMID 31956295, 2020). "To uncover the biological function of MAP7, we detect the mRNA level of MAP7 in cervical cancer cell lines." (PMID 31956295, 2020). "We next analysed the correlation of MAP7 and the clinical stage of Cervical cancer, we next divided the whole cohort into 4 groups according to the clinical stage." (PMID 31956295, 2020). "MAP7 promotes migration and invasion and progression of human cervical cancer through modulating the autophagy pathway." (PMID 31956295, 2020). "An increased level of MAP7 is a marker of poor prognosis in leukemia and cervical cancers." (PMID 32823874, 2020). "Moreover, it was shown that MAP7 promotes migration and invasiveness of cervical cancer cell lines by inducing EMT transition." (PMID 32823874, 2020). "The function of MAP7 in human cervical cancer (CC) was unknown." (PMID 31956295, 2020). "Hence, we examine the level of MAP7 in cervical cancer and its’ correlation with prognosis." (PMID 31956295, 2020). "MAP7 and its paralogue MAP7D1 regulate the migration and invasion of gastric cancer cells and the migration, adhesion, and cell cycle progression of cervical cancer cells through NF-κB and Wnt5α signaling." (PMID 38726137, 2024). "High expression of MAP7 (also known as ensconsin or E-MAP-115) has been reported to be an adverse prognostic biomarker for cytogenetically normal acute myeloid leukemia, stage II colon cancer, cervical cancer and metastatic endometrial cancer." (PMID 36852271, 2023).
acute myeloid leukemia (7 papers, 2016 to 2023). Acute myeloid leukemia (AML) is a group of neoplasms arising from precursor cells committed to the myeloid cell-line differentiation. "High MAP7 expression has been shown to be an adverse prognostic biomarker for cytogenetically normal acute myeloid leukemia." (PMID 32760221, 2020). "Studies showed that MAP7 was upregulated in young patients with cytogenetically normal acute myeloid leukemia and predicts poor outcome." (PMID 31956295, 2020). "In young patients with cytogenetically normal acute myeloid leukemia, high MAP7 expression is also predictive of adverse prognosis." (PMID 32760221, 2020). "High expression of MAP7 predicts the tumor recurrence and adverse outcomes in colon cancer and is related to a poor prognosis in patients with cytogenetically normal acute myeloid leukemia." (PMID 30065754, 2018). "In this study, we identified the prognostic significance of MAP7 expression in cytogenetically normal acute myeloid leukemia (CN-AML) patients (aged <60 years) based on several microarray datasets." (PMID 27686215, 2016). "Besides, other studies have shown that in cytogenetically normal patients with acute myeloid leukemia (AML), patients with high mRNA transcription levels of MAP7 are correlated with adverse OS compared to those with low MAP7 expression." (PMID 34660263, 2021).
colon cancer (6 papers, 2013 to 2023). "Moreover, high MAP7 expression has been associated with tumor recurrence and poor prognosis in Stage II colon cancer patients." (PMID 23941513, 2013). "Similarly, in Stage II colon cancer patients, higher expression level of MAP7 was related to worse prognosis." (PMID 32760221, 2020).
breast carcinoma (4 papers, 2023 to 2024). "Additionally, in breast cancer, MAP7 upregulation is associated with paclitaxel resistance, while its downregulation inhibits cell viability, motility, and invasion, and enhances apoptosis in paclitaxel-resistant cells." (PMID 38726137, 2024). "First, we analyzed the mRNA expression levels of all MAP7 members in TCGA breast cancer dataset (TCGA-BRCA) using the UCSC Xena platform." (PMID 37550720, 2023).
gastric cancer (3 papers, 2022 to 2024). A primary or metastatic malignant neoplasm involving the stomach. "In gastric carcinoma, circ_0042881 induced the malignant development of tumor cells through serving as miR-16 sponge to depress its target genes, the microtubule-associated protein 7 (MAP7) and AKT serine/threonine kinase 3 (AKT3)." (PMID 37626035, 2023).
endometrial cancer (2 papers, 2013 to 2020). Primary or metastatic malignant neoplasm involving the endometrium (mucous membrane that lines the endometrial cavity). "Previously, MAP7 was identified one out of 15 genes which were obviously up-regulated in metastatic endometrial cancer using a 22K Affymetrix array." (PMID 32760221, 2020). "In support of a potential role for MAP7 in metastatic growth, this gene was recently identified as one out of only fifteen that was highly upregulated in metastatic endometrial cancer using a 22 K Affymetrix array." (PMID 23941513, 2013).
Infertility (2 papers, 2019 to 2022). "Mutations in Map7 have been associated with male sterility, but Map3k5 homozygote mice have been reported to be fertile, suggesting that the loss of the first exon of Map7 is affecting MAP7 protein function, resulting in the observed infertility in rhme affected males." (PMID 35296311, 2022).
lymph node metastasis (2 papers, 2020). "In addition, univariate analysis revealed that MAP7 expression (p = 0.002), tumor size (p = 0.009), and lymph node metastasis (p = 0.002) were remarkably associated with overall survival of CC patients." (PMID 32760221, 2020). "Multivariate analysis indicated that MAP7 expression (p = 0.001) and lymph node metastasis (p = 0.002) may serve as independent predictors of worse survival of patients with CC." (PMID 32760221, 2020). "MAP7 was correlated with the clinical stage and tumor size and lymph node metastasis." (PMID 31956295, 2020).
neuroblastoma (2 papers, 2022 to 2025). Neuroblastoma (NB) is the most common solid, extracranial childhood tumor. "In line with the findings of the GEO2R analysis of the GSE45547 dataset, the expression of MAP7 related to neuronal differentiation is significantly increased in stage 4S neuroblastoma compared to stage 4 neuroblastoma." (PMID 41189817, 2025). "For this experiment, we used a mouse neuroblastoma cell line, N1-E115, in which the expression of Map7d2 and Map7d1, but not Map7 and Map7d3, was detected by quantitative real-time PCR (RT-qPCR)." (PMID 35470240, 2022). "We also examined the cellular functions of Map7D2 using the N1-E115 mouse neuroblastoma cell line, which expresses both Map7D2 and Map7D1 but not Map7 nor Map7D3." (PMID 35470240, 2022).
ovarian carcinoma (2 papers, 2024 to 2025). A malignant neoplasm originating from the surface ovarian epithelium. "KEGG enrichment analysis linked MAP7 knockdown to platinum drug resistance in ovarian cancer cells." (PMID 38726137, 2024). "A deeper dive into the association between MAP7 expression and clinicopathological traits among 98 ovarian cancer patients disclosed a significant correlation with patient age and FIGO stage, revealing elevated expression in older individuals and advanced disease stages." (PMID 38726137, 2024). "Our approach encompasses analyzing MAP7's expression levels across various datasets and clinical specimens, evaluating its association with patient outcomes, and probing its influence on ovarian cancer cell dynamics such as proliferation, migration, invasion, and apoptosis." (PMID 38726137, 2024). "MAP7 also plays a role in cisplatin resistance in ovarian cancer by modulating the Wnt/β-catenin pathway." (PMID 41465326, 2025). "To decipher MAP7's mechanistic influence in ovarian cancer, we employed GSEA enrichment analysis on ovarian cancer samples from the TCGA database (n = 594), categorizing them based on MAP7 expression levels." (PMID 38726137, 2024). "We have identified significant upregulation of MAP7 in ovarian cancer tissues, which correlates with advanced disease stages, higher pathological grades, and unfavorable prognoses." (PMID 38726137, 2024). "In our investigation, we found that elevated MAP7 expression in ovarian cancer (OC) correlates with poor prognosis." (PMID 38726137, 2024). "Our preliminary data analysis revealed that MAP7 is significantly overexpressed in ovarian cancer tissues compared to normal ovarian tissues." (PMID 38726137, 2024). "To elucidate MAP7's role in EMT within ovarian cancer, we analyzed EMT marker protein expression via Western blot." (PMID 38726137, 2024). "It was observed that ovarian cancer specimens exhibit markedly elevated mRNA levels of MAP7 compared to normal ovarian tissues." (PMID 38726137, 2024). "In our current study, we observed an upregulation and predominant nuclear localization of MAP7 in cisplatin-resistant A2780-DDP ovarian cancer cells, implicating its significant role in mediating drug resistance." (PMID 38726137, 2024). "Our findings position MAP7 as a pivotal element in ovarian cancer advancement and cisplatin resistance, primarily through its modulation of EMT and the Wnt/β-catenin pathway." (PMID 38726137, 2024). "Subsequent evaluations, utilizing CCK-8 proliferation assays and colony formation tests, illustrated a marked decline in ovarian cancer cell proliferation post-MAP7 knockdown, substantiating the gene's contributory role to cell growth." (PMID 38726137, 2024). "This upsurge in MAP7 expression was substantiated by analyses of two independent ovarian cancer patient cohorts (GSE27651 and GSE66957) employing R language." (PMID 38726137, 2024). "In summary, our research sheds light on CBY1 as a crucial nuclear target for MAP7 within cisplatin-resistant A2780-DDP ovarian cancer cells." (PMID 38726137, 2024). "These comprehensive findings collectively affirm that MAP7 promotes the proliferation, migration, and invasion of ovarian cancer cells, concurrently impeding apoptotic processes." (PMID 38726137, 2024). "Developing small molecule inhibitors targeting MAP7 directly to curb its function in ovarian cancer cells may offer novel drug targets for tackling cisplatin-resistant ovarian cancer." (PMID 38726137, 2024). "Strategies aimed at MAP7 could represent a new frontier in combating chemotherapy resistance in ovarian cancer, emphasizing its significance in crafting complementary treatments for this disease." (PMID 38726137, 2024). "Notably, among 86 serous ovarian cancer cases, MAP7 expression was predominantly higher in high-grade tumors, highlighting its potential role in the progression and aggressiveness of ovarian cancer." (PMID 38726137, 2024).
ovarian carcinoma (continued). "Additionally, comparative assessments of MAP7 protein levels across 142 ovarian cyst and 98 ovarian cancer specimens indicated a pronounced increase in ovarian cancer tissues relative to ovarian cyst tissues, aligning with the mRNA expression trends observed in public datasets." (PMID 38726137, 2024). "Immunofluorescence experiments revealed heightened MAP7 protein expression in ovarian cancer A2780-DDP cells, predominantly localized to the nucleus, indicating nuclear MAP7's key role in cisplatin resistance." (PMID 38726137, 2024). "Conversely, MAP7 overexpression in ES-2 and OVCAR8 cells resulted in increased expression of these components, pointing to MAP7's role in activating the Wnt/β-catenin pathway and thereby promoting EMT in ovarian cancer cells." (PMID 38726137, 2024). "This supports the hypothesis that MAP7's nuclear presence, particularly its interaction with CBY1, contributes significantly to the modulation of the Wnt/β-catenin pathway and the development of cisplatin resistance in ovarian cancer cells." (PMID 38726137, 2024).
kidney cancer (1 paper, 2022). Primary or metastatic malignant neoplasm involving the kidney. "In our study, we found MAP7, SLC16A12, and SLC27A2 in kidney cancer cells when compared with normal kidney cells, which agreed with the results of the TCGA-KIRC." (PMID 36620592, 2022). "The results revealed that the basal expression profiles of MAP7, SLC16A12, and SLC3A1 were high in kidney cancer cells." (PMID 36620592, 2022).
lung adenocarcinoma (1 paper, 2015). A carcinoma that arises from the lung and is characterized by the presence of malignant glandular epithelial cells. "Previous studies have shown that transfecting the human lung adenocarcinoma cell line A549 with a MAP7 overexpressing plasmid significantly increases the cell proliferation." (PMID 26248031, 2015).
male infertility (1 paper, 2022). The inability of the male to effect fertilization of an ovum after a specified period of unprotected intercourse. "For the rhme deletion, existing expression data and the associated male infertility support Map7 as the best candidate gene." (PMID 35296311, 2022).
Obesity (1 paper, 2020). Accumulation of substantial excess body fat. "Although there are no data to confirm that MAP7 and ZNF429 are relationship to obesity or T2DM, we believe that they may be closely related to the pathogenesis of O‐T2DM due to their mutations in the exon region and their significant changes in transcriptome expression levels." (PMID 31957265, 2020).
osteosarcoma (1 paper, 2024). A usually aggressive malignant bone-forming mesenchymal neoplasm, predominantly affecting adolescents and young adults. "We discovered that MAP7 expression was significantly reduced in osteosarcoma cells, and low expression of MAP7 was associated with poor prognosis of osteosarcoma patients." (PMID 39980969, 2024). "Subsequently, we analyzed the prognostic role of MAP7 in osteosarcoma patients and found that the expression of MAP7 was downregulated in osteosarcoma samples compared to normal samples in the GSE16088 and GSE28424 datasets." (PMID 39980969, 2024). "In the TARGET and GSE39055 cohort, we divided osteosarcoma patients into MAP7high and MAP7low groups according to the median expression value of MAP7." (PMID 39980969, 2024). "Accordingly, to investigate the role of MAP7 in osteosarcoma progression, we established an MAP7-overexpressing osteosarcoma cell model in the SAOS-2 cell." (PMID 39980969, 2024). "Moreover, the overexpression of MAP7 significantly reduced cell proliferation, the ability of cell migration, and invasion in osteosarcoma cells." (PMID 39980969, 2024). "Finally, we discovered significant reduction in MAP7 expression in osteosarcoma cells, and patients with low MAP7 expression had poor prognosis." (PMID 39980969, 2024). "Finally, to explore the role of MAP7 in the progression of osteosarcoma, we first confirmed the expression of MAP7 mRNA in several osteosarcoma cell lines." (PMID 39980969, 2024). "Moreover, MAP7 might serve as a prognostic marker for osteosarcoma patients." (PMID 39980969, 2024). "Thus, we hypothesized that MAP7 might also play a critical role in the progression of osteosarcoma." (PMID 39980969, 2024). "Although the roles of SP110, HHAT, MORC4, PAGE5, MAP7, and CAMK1G in osteosarcoma have rarely been reported, their involvement in other types of cancer has been revealed." (PMID 39980969, 2024). "Furthermore, MAP7 might be a prognostic marker for osteosarcoma patients." (PMID 39980969, 2024).
schizophrenia (1 paper, 2020). A major psychotic disorder characterized by abnormalities in the perception or expression of reality. "Another of the candidate genes ENPP1 has been linked to learning and memory abilities in mice, while MAP7 has been shown to play a critical role in the developmental regulation of neural axon branch maturation (MAP7,) and is also involved in schizophrenia (MAP7,)." (PMID 33138119, 2020).